FBXO30 (F-box protein 30)
Description:
Substrate-recognition component of the SCF (SKP1-CUL1-F-box protein)-type E3 ubiquitin ligase complex. Required for muscle atrophy following denervation.
Synonyms: FBX30; MGC21674
Tractability: PROTAC: UniProt records ubiquitination sites on it; ubiquitination databases record sites on it; its protein half-life has been measured.
Gene: Protein-coding gene on chromosome 6 (145,793,502 to 145,815,267, reverse strand). Ensembl gene ENSG00000118496.
Subcellular location (Human Protein Atlas): Microtubules
Pathways (Reactome):
Immune System: Antigen processing: Ubiquitination & Proteasome degradation
Metabolism of proteins: Neddylation
Gene Ontology:
Molecular function: protein binding; ubiquitin protein ligase activity; zinc ion binding
Biological process: SCF-dependent proteasomal ubiquitin-dependent protein catabolic process; protein ubiquitination
Cellular component: cytosol; SCF ubiquitin ligase complex
Genetic constraint (gnomAD): Loss-of-function variants: 21 observed, 60.6 expected, observed/expected ratio (o/e) 0.35, 90% interval 0.25 to 0.5. The upper end of that interval is the gene's LOEUF score, 0.5, which puts it in group 2 of 6, group 1 being the genes least tolerant of losing a copy. Missense variants: 744 observed, 947.68 expected, observed/expected ratio (o/e) 0.79, 90% interval 0.74 to 0.83. Synonymous variants: 309 observed, 330.64 expected, observed/expected ratio (o/e) 0.93, 90% interval 0.85 to 1.03.
Homologues: Orthologues: chimpanzee FBXO30 (99% identical), macaque FBXO30 (95% identical), pig FBXO30 (93% identical), guinea pig FBXO30 (91% identical), rabbit FBXO30 (90% identical), mouse Fbxo30 (88% identical), rat Fbxo30 (88% identical), tropical clawed frog fbxo30 (68% identical), zebrafish fbxo30a (60% identical), Caenorhabditis elegans C10E2.2 (16% identical). Paralogues in human: FBXO40 (31% identical).
Diseases named in the same sentence as FBXO30 in open-access papers:
FBXO30 is named in the same sentence as 14 diseases in open-access papers, as found by Europe PMC text mining. Sharing a sentence is not in itself a finding about the gene and the disease. The quoted sentences say what the papers report.
Sepsis (2 papers, 2020 to 2023). Sepsis is defined as life-threatening organ dysfunction caused by a dysregulated host response to infection. "Fbxo30, Fbxo32, and Trim63 expression was increased in both muscles of septic mice, compared with sham controls, indicating that sepsis leads to an activation of the atrophy program in muscle." (PMID 31441598, 2020). "In order to investigate if the atrophy program is activated in skeletal muscle during sepsis, we quantitated the expression of Fbxo30, Fbxo32, and Trim63 in both muscles of sham and CLP mice." (PMID 31441598, 2020). "Besides the atrophy markers Trim63/MuRF1, Fbxo32/Atrogin‐1, and Fbxo30/MuSA1 (all induced >5‐fold by sepsis, P < 0.001) the expression of Spsb1 was significantly increased after 24 and 96 h of sepsis (24 h: 20‐fold; 96 h: 34‐fold, P < 0.001)." (PMID 37209006, 2023).
acute kidney injury (1 paper, 2025). Sudden and sustained deterioration of the kidney function characterized by decreased glomerular filtration rate, increased serum creatinine or oliguria. "In a gentamicin-induced acute kidney injury experiment in rats, expression of MuRF1 and MAFbx was increased in muscle and correlated with AKI severity, whereas the expression of the other three E3 ligases (Nedd4, Trim32, and Fbxo30 / MUSA1) was irrelevant." (PMID 40225869, 2025).
anencephaly (1 paper, 2019). A rare neural tube defect during pregnancy, resulting in the absence of a large portion of the brain and skull in the fetus. "Western blot analysis of ten anencephaly subjects compared with age and gender-matched controls revealed that FBXO30 levels were decreased in most anencephaly samples ranging from 10 to 80%." (PMID 31320612, 2019).
Cachexia (1 paper, 2019). Severe weight loss, wasting of muscle, loss of appetite, and general debility related to a chronic disease. "To further validate cachexia development using established molecular markers of muscle wasting, we examined the expression of genes that encode ubiquitin ligases associated with muscle proteolysis (Trim63/MuRF1, Fbxo32/MAFBx, Fbxo31, Fbxo30/Musa1)." (PMID 31861290, 2019).
nasopharyngeal carcinoma (1 paper, 2019). A carcinoma arising from the nasopharyngeal epithelium. "Although we found FBXO30 to be significantly downregulated in PCa versus nonmalignant PCa tissue samples in the cohort from TCGA, others have reported FBXO30 as upregulated in PCa and for example in nasopharyngeal cancer." (PMID 30866497, 2019).
tumor (7 papers, 2014 to 2025). "In the tumor-bearing animals, treatment with WFA led to a statistically significant dose-dependent transcriptional downregulation of Fbxo30, Fbxo32, Trim63, and Traf6 compared to the tumor-bearing vehicle-treated group (p < 0.0001 for all comparisons)." (PMID 33718372, 2021). "The WFA 4 mg/kg group exhibited a significant reduction in relative gene expression of Fbxo30, Fbxo32, Trim63, and Traf6 compared to the tumor-free vehicle-treated group (p < 0.0001, p = 0.04, p = 0.02, p < 0.0001, respectively)." (PMID 33718372, 2021). "Within the tumor-free groups, there was a significant reduction in the relative transcriptional expression of Traf6 and Fbxo30 in the WFA 2 mg/kg group compared to the vehicle-treated group (p < 0.05 for both comparisons)." (PMID 33718372, 2021). "Specificity/sensitivity for high tumor volume was 81%/71% for DOCK2, 71%/89% for HAPLN3, and 75%/77% for FBXO30." (PMID 32486483, 2020). "In contrast, methylated ctDNA was detected in 89.2% (25/28) of mPCa patients with high tumor volume; 20/28 (71.4%) patients positive for DOCK2, 25/28 (89.2%) positive for HAPLN3, and 13/17 (76.5%) positive for FBXO30." (PMID 32486483, 2020). "In de novo mPCa patients, we detected methylated ctDNA in 32.3% of the patients with low tumor volume and in 89.3% of patients with high tumor volume using the DOCK2, HAPLN3, and FBXO30 assays (positive for at least one assay)." (PMID 32486483, 2020). "Interestingly, genes encoding ubiquitin ligases (Trim63, Fbxo32/MAFBx, Fbxo31, and Fbxo30/Musa1) that target muscle proteins and serve as markers of muscle atrophy were found to be transcriptionally upregulated in the gastrocnemius muscles from the tumor‐bearing mice." (PMID 32730698, 2020). "In mPCa patients with low tumor volume, methylated ctDNA was detected in a total of 32.3% (10/31) of the patients, with 6/31 (19.4%) patients positive for DOCK2, 9/31 (29.0%) positive for HAPLN3, and 3/12 (25.0%) positive for FBXO30." (PMID 32486483, 2020).
myopathy (1 paper, 2023). A disease of the muscle in which the muscle fibers do not function properly. "So far only Fbxo9, being upregulated in a hindlimb unloading model and the association of Fbxo30 in Nebulin-mediated myopathy are known." (PMID 36969608, 2023).
FBXO30 also shares sentences with these, for which no sentence is quoted: cancer (2 papers); benign prostatic hyperplasia (1); epilepsy (1); lung carcinoma (1); mastitis (1); metabolic disorders (1); neural tube defect (1).